TRAF5 (TNF receptor associated factor 5)
Diseases named in the same sentence as TRAF5 in open-access papers (continued):
Sharing a sentence is not in itself a finding about the gene and the disease.
cancer (17 papers, 2018 to 2025). A tumor composed of atypical neoplastic, often pleomorphic cells that invade other tissues. "Approximately 36% (57/160) of the coding-altering mutations of TRAF5 are recurrent in human cancers." (PMID 30294322, 2018). "There are 188 different mutations of TRAF5 detected in human cancers, comprising 85% (160/188) mutations that alter the amino acid sequence of TRAF5 and 15% (28/188) coding silent mutations." (PMID 30294322, 2018). "Studies demonstrated that TRAF5 is closely linked to the onset and progression of cancer." (PMID 40003916, 2025). "In this study, TRAF5 was implicated in oncogenic processes in several cancers." (PMID 38825674, 2024). "This analysis revealed that TRAF1, TRAF2, TRAF3, TRAF4, TRAF6, and TRAF7 exhibit higher expression levels in cancer tissues, whereas TRAF5 is expressed at lower levels in these tissues." (PMID 38825674, 2024). "In turn, the activation of the NF-κB/p65 pathway and NF-κ B/c-Re l pathway mediated by TRAF5 in normal vulvar tissues and the expression of TRAF5 protein in corresponding cancer tissues decreased accordingly." (PMID 37904442, 2023). "Meanwhile, TRAF5 is directly involved in NF-κB activation and protection from cancer cell death, displaying a slightly different mechanism in the AKT-NF-κB pathway." (PMID 34983361, 2022). "Both TRAF4 and TRAF5 function as activators in the inflammatory process and promote cancer development." (PMID 34983361, 2022). "TRAF5 is closely related to the occurrence and development of cancer." (PMID 40003916, 2025). "Although direct evidence connecting IRF9 to BLCA is currently sparse, its function in regulating immune responses and potential interactions with other signaling molecules, such as TRAF5, could offer valuable insights into its role in cancer progression." (PMID 40893939, 2025). "Deep deletion, truncation and fusion of TRAF5 are rare events in human cancers." (PMID 30294322, 2018). "Thus, reducing the TRAF5 level has been a promising strategy for cancer treatment." (PMID 37366426, 2023). "In addition to the signaling pathways of B cells and T cells revealed by the in vivo studies of TRAF5−/− mice, a number of TRAF5-dependent signaling pathways have been proposed based on the studies of patient samples, cultured human cancer cells or their xenografts in immunodeficient mice." (PMID 30294322, 2018). "IL33 was found to have widespread positive correlations in several cancer types, whereas IRF9 and TRAF5 demonstrated more heterogeneous correlation profiles." (PMID 40893939, 2025). "The analysis of 33 cancer types revealed that TRAF2, TRAF3, TRAF4, and TRAF7 are predominantly overexpressed, whereas TRAF1, TRAF5, and TRAF6 exhibit lower expression levels." (PMID 38825674, 2024). "Mechanistically, knocking down TRAF4, TRAF5, or TRAF6 in retinoic acid-treated cancer cell lines increased the levels of procaspase 9 and induced cell apoptosis." (PMID 37389738, 2023). "Gain-of-function alterations (gene amplification and overexpression) are common for TRAF1, TRAF4, TRAF5, and TRAF6 in human cancers, and are also identified for TRAF2 in epithelial cancers." (PMID 30294322, 2018). "We also demonstrated that inhibiting TRAF4, TRAF5, or TRAF6 could suppress cancer cell proliferation, highlighting the critical oncogenic role of TRAFs in carcinogenesis." (PMID 37389738, 2023).
infection (7 papers, 2008 to 2025). The state of being infected such as from the introduction of a foreign agent such as serum, vaccine, antigenic substance or organism. "At 3 h post-infection, the TNF receptor-associated factor 5 (TRAF5) -like DEC is down-regulated 230.6 times (Robust Exact Test, FDR = 1.79E− 2), but isoforms are up-regulated at 3, 6 and 12 h." (PMID 33167855, 2020). "Nile tilapia TRAF5 mRNAs were significantly up-regulated at 12 h after infection with S. agalactiae." (PMID 37176078, 2023). "TRAF5 transcript levels where the most significantly and consistently modulated during repeated immunising infections and remained low during the challenge infection." (PMID 20950493, 2010). "There was some additional down-regulation of TRAF5 expression during the challenge infection (PI_I3, -2.43 compared to PI_C3, -3.41) but for the other genes, maximum down-regulation had occurred by the third immunising infection." (PMID 20950493, 2010). "Our data clearly show the development of Th2-type effector cytokine response during repeated immunising infections which is supported by the strong down-regulation of TRAF5 signalling and the up-regulation of the IL-18 binding protein." (PMID 20950493, 2010). "In particular, genes that are known to activate NF-kappaB, e.g., TLR1, TLR3, TRAF5 and CD14, showed increased expression over infection time." (PMID 36544767, 2022). "In general, DCs were more responsive than Mφs to infection, with more genes induced, such as SOCS2, ISG20, TRAF5 and IRF4." (PMID 18167562, 2008). "Our results demonstrate a clear inactivation of the TRAF5 and TRAF6 genes when infection occurs after immunization, in contrast to infection without prior vaccination." (PMID 40136419, 2025). "We found that TRAF2, 3, and 6 but not TRAF5 showed induced interaction with MAVS, confirming that multiple TRAFs were recruited to MAVS upon infection." (PMID 29125880, 2017).
TRAF5 also shares sentences with these, for which no sentence is quoted: ovarian carcinoma (3 papers); ankylosing spondylitis (2); autoimmune disorders (2); breast carcinoma (2); acute myeloid leukemia (1); alcoholic steatohepatitis (1); bladder cancer (1); colon adenocarcinoma (1); diffuse large B-cell lymphoma (1); gastric cancer (1); gastric tumor (1); Glioblastoma multiforme (1); heart disease (1); Hepatitis (1); Hodgkins lymphoma (1); inflammation (1); ischemic stroke (1); lymphoma (1); metabolic disorders (1); nevus (1); non-alcoholic fatty liver disease (1); psoriasis (1); psoriatic arthritis (1); steatosis (1); type 2 diabetes (1); uterine corpus endometrial carcinoma (1).